EGFR (epidermal growth factor receptor)
Diseases named in the same sentence as EGFR in open-access papers (continued):
Sharing a sentence is not in itself a finding about the gene and the disease.
tumor (continued). "While anti-HER2 drugs, such as trastuzumab as monotherapy, have not demonstrated tumour regression in clinical trials, a combination therapy with an EGFR inhibitor achieved tumour shrinkage." (PMID 35267469, 2022). "To further clarify the anti-tumor effects of Fasudil in combination with gefitinib, we examined the effects of this drug combination on EGFR/PI3K/AKT signaling pathways in HCC827GR and H1975 cells." (PMID 36230634, 2022). "We performed gene expression analysis on these cells and found that P2ry14 mRNA is elevated in p75+/EGFR+ SCP-like tumor-initiating cells." (PMID 35311647, 2022). "This study demonstrated that EGFR-TKIs are well-tolerated in patients with poor PS and have comparable anti-tumor activity." (PMID 35158940, 2022). "Epidermal growth factor receptor (EGFR), for instance, was demonstrated to enhance its oncogenic role in cancer progression by suppressing microRNA (miRNA) maturation of tumor suppressors when associated with phosphorylated AGO2 under hypoxia." (PMID 35158774, 2022). "Molecular characterization showed that ITGB4 was upregulated in primary tumors and metastases compared to normal mucosa and correlated with EGFR/MAPK activity in tumor bulk and single malignant cells." (PMID 36076232, 2022). "Such as HER2, MUC1, EGFR as tumor targets of pan-cancer, are also highly expressed in BC tissues and can be used as a therapeutic target of BC." (PMID 35860578, 2022). "Conversely, Src kinase is one of the downstream signal molecules mediating HER3 (coupled with EGFR or HER2) triggered tumor progression." (PMID 35625759, 2022). "SSNs complexed with EGFR siRNA demonstrated a modest tumour growth compared to the other three groups, with an average tumour volume of ~1182.80 mm3." (PMID 36412852, 2022). "Since both FOLFOXIRI and anti-EGFR target therapy were considered to be related to more rapid tumor responses, we conducted this meta-analysis to assess the efficacy and safety of their combination." (PMID 35965307, 2022). "Unlike NK cells transduced with an empty vector, frozen, easily accessible off-the-shelf EGFR-CAR NK cells demonstrated improved killing of tumor cells." (PMID 36703982, 2022). "Among the NAC-induced miRNAs in non-responders is miR-539-5p, which has been shown to act as a tumor suppressor in BC by targeting EGFR, LAMA4, and SP1 thus leading to the inhibition of proliferation and migration of BC cells." (PMID 36387168, 2022). "Another important target at the tumor level is epidermal growth factor receptor (EGFR) that is overexpressed in a variety of tumors." (PMID 35745807, 2022). "We showed that TFAP2C knockdown enhanced the anti-tumor effects of cisplatin in vivo and in vitro by reducing the levels of EGFR and NF-κB activation, thereby providing a new idea for improving the efficacy of cisplatin." (PMID 36230734, 2022). "the activation of EGFR mediated a variety of intracellular downstream signals, contributing to tumor aggression and resistance to first-line chemotherapies." (PMID 36230833, 2022). "Briefly, EGFR expression on monocytes, macrophages, skin keratinocytes, tumor cells, and in various epithelial tissues were identified from functional and IHC staining data." (PMID 35754500, 2022). "Most strikingly, combined simultaneous blockade of EGFR and anti-PD-1 (aPD-1) enhanced tumour treatment response in a transgenic mouse model of EGFR-driven NSCLC." (PMID 36010935, 2022). "Abnormal activation or expression of EGFR or its ligands promotes tumor growth, invasion, and metastasis, leading to a more aggressive phenotype and is often associated with poor prognosis and shorter survival." (PMID 36499115, 2022). "In particular, miR-7-5p acts as tumor suppressor in signaling pathways with a crucial role in cancer (EGFR/MAPK, PI3K/Akt, Wnt, and others), inhibiting cell survival, proliferation, and migration." (PMID 35347579, 2022).
tumor (continued). "By engineering EGFR-directed BiTEs, which tether T cells to tumor cells, into the EGFRvIII-CAR T cells, producing a dual-targeted platform to prevent antigen escape." (PMID 35428347, 2022). "Since miR-223 then targets EGF expression, Palbociclib treatment eventually results in autocrine and paracrine dampening of EGFR pathway in tumor cells as well as in the tumor microenvironment." (PMID 35712501, 2022). "Tumor cells with high EGFR expression were efficiently phagocytosed by macrophages, even in the presence of low anti-EGFR mAb concentrations." (PMID 35035479, 2022). "The authors demonstrated that the inhibition of oncogenic EGFR leads to binding of TET1 to tumor suppressor promoters and induces their re-expression through active DNA demethylation." (PMID 35269796, 2022). "Our study reveals that the EGFR-TKI-treatment-related oncogenic pathway changes contributing to EGFR-TKI resistance in EGFR-mutant NSCLC are paradoxically attributed to the targeting of tumor cells by an activated immune system." (PMID 36612121, 2022). "This overexpression is thought to be relevant for tumor progression, making EGFR a therapeutic target." (PMID 35109825, 2022). "Lipid rafts often provide signalling platforms for growth factor receptors, such as EGFR, in tumour development." (PMID 36497413, 2022). "This technology uses the CAR construct to locally deliver BiTE molecules, which are bispecific antibodies for EGFR and T‐cells, that activate bystander T cells to kill EGFR‐expressing tumour cells." (PMID 36495108, 2022). "The ability of IRDye800CW-conjugated cetuximab in detecting EGFR-overexpressing tumors has already been reported in both preclinical and clinical studies, and it has been found to be a suitable tumor-detecting agent." (PMID 35517713, 2022). "Endogenous EGFR is located on human chromosome 7, and metaphase spreads of the two tumour lines showed 3–6 copies of chromosome 7 in E26 and frequently 3 copies in E28." (PMID 36476408, 2022). "For expression of HIF-1α, EGFR, pAKT and pMAPK, tumor samples were analyzed by immunohistochemistry in tissues microarrays." (PMID 36358811, 2022). "as monotherapy and in combination therapy, the latter showing synergistic anti-tumor effects and higher toxicity profile than other EGFR-directed monoclonal antibodies." (PMID 35978836, 2022). "In contrast with the previous thought of KRAS mutant independency from upstream RTK, recent data demonstrate that the genetic abrogation of EGFR resulted in impaired tumor growth of KRAS mutant NSCLC models." (PMID 36358848, 2022). "HGF targeting antibodies, including rilotumumab (AMG-102), ficlatuzumab, TAK-701, and YYB-101, bind to HGF and prevent c-Met attachment, leading to the induction of synergistic anti-tumor responses combined with other TKIs and EGFR inhibitors." (PMID 35986321, 2022). "Cetuximab, an anti-epidermal growth factor receptor (EGFR) mAb, induces apoptosis in tumor cells by blocking ligand binding and receptor dimerization." (PMID 35328459, 2022). "When EGFR is activated, a variety of transcription factors are activated through the activation of downstream signalings to promote the progression of tumor cells." (PMID 36092699, 2022). "VEGF induces not only tumor angiogenesis, but also promotes the proliferation of EGFR-mutant cancer cells and affects the immune suppressive network." (PMID 35698083, 2022). "We revealed that TGFα-EGFR carcinogenic action is being enhanced in BC cases of low WWOX expression which is supposed to be a very common event in this tumor." (PMID 35290621, 2022). "We performed the meta‐analysis on EGFR positive tumor NSCLC from 35 studies and noted that EGFR+ in both tumor tissue and plasma at baseline is the worse prognostic factor for PFS and OS." (PMID 34427045, 2022). "In a previous study, EGFR was hyperphosphorylated in 4 out of 5 tumours from patients with acquired or intrinsic resistance to vemurafenib, leading to a hyperactivation of the STAT3 pathway." (PMID 36084109, 2022).
tumor (continued). "At the same time, β-catenin can regulate the expression of EGFR and promote the migration of tumor cells." (PMID 36387067, 2022). "The approach employs a late fusion strategy to bring all modules together and predict tumor size in the context of two treatment modalities: anti-EGFR treatment and immunotherapy." (PMID 36274654, 2022). "For example, for patients with NSCLC to start immediately with the first-line treatment, EGFR tumor genotyping is essential, which also greatly impacts clinical management." (PMID 36293374, 2022). "In the future, molecular evaluation of tumor biopsies at progression should be a critical factor to better characterize the relationship between resistance mechanisms to EGFR-TKIs and plasma drug exposure." (PMID 36145591, 2022). "Accordingly, we anticipated the inhibition of EGFR signaling can influence the secretion of VEGF from the EGFR mutant tumor cells and consequently regulate intratumoral vessel growth." (PMID 35501907, 2022). "Epidermal growth factor receptor (EGFR) is a cancer-promoting tumour marker that regulates the homeostasis and growth of epithelial tissues and cells." (PMID 35260672, 2022). "Treatment with EGFR-TKI alone until tumour progression and patients who responded to EGFR-TKI treatment received TRT for lung tumours afterward were administered to patients in groups 1 (n=1180) and 2 (n=295), respectively." (PMID 35646640, 2022). "On the other hand, fibroblast growth factor receptor 1 (FGFR1) is commonly expressed in all types of cancer and is involved in tumor progression and epithelial-to-mesenchymal transition-related drug resistance to EGFR-TKIs." (PMID 36015232, 2022). "The expression of EGFR/MET was up-regulated in circulating tumor microemboli (CTM) to accelerate IL-8 production and resistance to the lethal effect of leukocytes." (PMID 35428350, 2022). "The EGFR T790M detection rate by ddPCR assay was 32.3% (65/201) in plasma samples and 32.8% (66/201) in the paired tumor tissue samples." (PMID 36776375, 2022). "Patients with a TERT promoter wild type and EGFR wild type tumor had approximately double the overall survival of patients harboring a TERT promoter wild type tumor with EGFR alteration, with an overall survival of 26.6 vs. 13.3 months." (PMID 36233828, 2022). "In the frame of EGFR-mediated EMT, ITGB4 was identified as a mechanistic biomarker that is essential for local invasion, is associated with tumor budding, is a target for antagonizing antibodies, and represents a novel predictive marker candidate." (PMID 36076232, 2022). "Here, our results highlighted that sizes of TNBC tumor spheres were declined after blockade of EGFR; overexpression of EGFR increased sizes of tumor spheroid." (PMID 35725558, 2022). "Survival in various tumor entities depends on EGFR signaling, which is strongly altered in about two thirds of sporadic CRC patients." (PMID 35448502, 2022). "Bispecific immuno-ligands, via NKp30 engagement, are more efficient against EGFR-overexpressing tumor cells than clinically approved cetuximab." (PMID 35078821, 2022). "In another study using RT-PCR to measure EGFR mRNA expression, a significant correlation was observed in EGFR mRNA expression levels between primary tumor and liver metastasis." (PMID 35902718, 2022). "Sesamin (1 g/kg, 8 wk the basal diet) supplementation in athymic mice reduced tumor size by around 23% compared to control through downregulating growth factor receptor including EGFR and HER2 and reducing pMAPK expression." (PMID 35223101, 2022). "Consistently, we found both EGFR signalling and Yki were activated by Toll‐7, and both were required for Toll‐7‐ induced tumour growth, which also depends on JNK." (PMID 35050535, 2022). "In HNSCC mouse xenografts, IL1-suppression by the drug anakinra was able to sensitize tumor cells toward EGFR inhibitor treatment." (PMID 35530351, 2022).
tumor (continued). "According to the promising preclinical results, a clinical study was conducted to evaluate the safety and anti-tumor activity of lenvatinib–gefitinib combination in 12 patients with EGFR high HCC." (PMID 36080304, 2022). "EGF induces EMT in cancers through the EGF/EGFR signaling pathway, thus promoting the invasion and metastasis of tumor cells." (PMID 35526240, 2022). "MiR-146a-5p inhibits epidermal growth factor receptor (EGFR) expression, angiogenesis, tumor proliferation, and migration." (PMID 35938167, 2022). "Nonetheless, this highlights the significant knowledge gaps in our understanding of the cross talk between EGFR and ion channels for continued tumour progression." (PMID 36497413, 2022). "Positive EGFR expression was reported when ≥ 10% of the tumor cells were stained with a moderate to strong intensity score." (PMID 36581931, 2022). "Compound 6b inhibited angiogenesis, tumor progression, metabolic reprograming, and metastasis by inhibiting EGFR by decreasing Hif-1α expression upon treatment." (PMID 36080307, 2022). "Together with the in vitro and in vivo assays, we concluded a sequence-dependent synergistic effect of aumolertinib and pemetrexed on EGFR-mutant tumor growth and metastasis." (PMID 35501907, 2022). "In pre-clinical studies, GammabodyTM molecules targeting CD40, CD1d and EGFR efficiently engage Vγ9Vδ2 T-cells to kill tumor cells expressing these antigens." (PMID 35784326, 2022). "Together, these data suggest that ATM activation occurs in human tumors surviving treatment with EGFR inhibitors, where it likely plays a tumor protective role." (PMID 35353542, 2022). "Nimotuzumab competes with EGFR to block downstream signalling pathways, inhibit tumour cell proliferation, promote tumour cell apoptosis, resist angiogenesis, and enhance the efficacy of radiotherapy or chemotherapy." (PMID 36263226, 2022). "The EGFR measured in tumour cells by IH or FISH can also be measured in plasma or serum and is routinely detected in patients with lung cancer." (PMID 36158981, 2022). "In a similar manner, EGFR aptamer-conjugated EVs loaded with survivin siRNA inhibited tumor growth in an orthotopic breast cancer mouse model." (PMID 36591444, 2022). "In cancer, it is observed that EGFR is overexpressed and results in increased cellular proliferation with decreased apoptosis, thereby promoting tumor growth." (PMID 35769445, 2022). "It confirms that potentiation of EGFR‐TKI by vascular‐targeted drugs exerts effects by inhibiting the growth of tumor blood vessels." (PMID 34855286, 2022). "High-affinity binding to both tumour targets, EGFR and PD-L1, as well as to IL-6R was observed via biolayer interferometry." (PMID 36439165, 2022). "We extracted RNA-Seq data from the TCGA database to compare the expression of EGFR in tumor tissues removed from ESCC patients with normal human esophageal tissues." (PMID 35163685, 2022). "Several trials indicated that EGFR mutations are associated with immunosuppressive TME, lower tumor mutation burden (TMB), and increased PD-L1 expression." (PMID 35742933, 2022). "In this work, we examine the functional links between drug distribution, molecular properties intrinsic to tumor cells, and the tumor microenvironment (TME) in brain metastases from EGFR-mutant NSCLC." (PMID 36509758, 2022). "They showed that, compared with free cisplatin, polymeric nanoparticles conjugated with anti-EGFR aptamer exhibited greater efficiency in tumor targeting and increased therapeutic outcomes." (PMID 35845934, 2022). "To overcome the adverse effects associated with systemic administration of STING agonists, we sought targeted delivery of the payload to tumor sites by conjugation to an antibody against EGFR, which is overexpressed in multiple tumor types." (PMID 36442099, 2022). "The expression levels of p/t-EGFR and cell proliferation marker Ki-67 were detected using immunohistochemistry to explore Huaier’s mechanism on tumor growth inhibition." (PMID 35470770, 2022).
tumor (continued). "Under cisplatin treatment conditions, TFAP2C knockdown led to lower levels of EGFR and NF-κB activation, enhancing the anti-tumor effect of cisplatin in BCa." (PMID 36230734, 2022). "At the same time, the abnormal expression of AQP5 can regulate the EGFR pathway and promote the proliferation of tumor cells." (PMID 35245343, 2022). "In sum, it is crucial and urgent to use the whole picture of the tumor to predict the potential resistance or the likelihood of rapid progression comprehensively before patients receive EGFR TKIs." (PMID 36052262, 2022). "Nimotuzumab, targeted to EGFR, is the recombinant humanized monoclonal antibody, which can strengthen chemotherapy sensibility, enhance RT efficacy, and inhibit tumor growth, metastasis, and local relapse." (PMID 35898885, 2022). "EGFR signaling pathway plays a significant role in tumor proliferation and angiogenesis in HCC pathogenesis." (PMID 35039485, 2022). "Patients harboring an EGFR mutation positive tumor are best treated with an EGFR tyrosine kinase inhibitor (EGFR TKI), as tumor responses are higher and more durable with EGFR TKI than with chemotherapy or immunotherapy." (PMID 35453931, 2022). "Epidermal growth factor receptor (EGFR) is another potential therapeutic target whose activation led to tumor cell proliferation, evasion of apoptosis, angiogenesis, and metastasis." (PMID 36517820, 2022). "EGFR expression was low in primary tumor and LN metastases (median TIS 3 and 2 respectively) and absent in LNs without metastases." (PMID 36581931, 2022). "FUT8 modifies the activities of both the hepatocyte growth factor receptor and EGFR and affects tumor growth and invasion." (PMID 35752750, 2022). "Recent genetic profiling studies of tumor tissues have found somatic mutations in genes such as the TERT, PTEN, and epidermal growth factor receptor (EGFR)." (PMID 36359238, 2022). "The activation of the cell surface protein kinases PDGFRA, PDGFRB and EGFR promotes cell proliferation in normal cells and is enhanced in certain tumour types, while their down-regulation is in accord with the cell cycle inhibition we uncovered." (PMID 35205253, 2022). "We aimed to use artificial intelligence (AI) models to predict EGFR mutations and ALK rearrangement status using common demographic features, pathology and serum tumor markers (STMs)." (PMID 35624472, 2022). "Here the authors show that small GTPase ARF6 mediates the trafficking of palmitoylated EGFR from Golgi to plasma membrane and the blockade of this sorting system inhibits the growth of EGFR overexpression tumours." (PMID 36224181, 2022). "Savolitinib, in combination with erlotinib, a first-generation EGFR–TKI inhibitor, showed substantial tumor inhibition in H441, an EGFR wild type model with MET amplification." (PMID 36551608, 2022). "EGFR-TKI treatment induces EGFR-mutant tumor cell death while simultaneously altering the tumor microenvironment through cytokine signaling." (PMID 36612121, 2022). "Often, tumor-associated cell-surface antigens or glycoproteins, such as EGFR, HER2, or PSMA, are used as tumor-homing targets, given that they are overexpressed on many tumors." (PMID 36276636, 2022). "EGFR is related to the inhibition of tumour cell proliferation, angiogenesis, tumour invasion, metastasis and apoptosis." (PMID 36176072, 2022). "In TN neoplasms, EGFR overexpression in the tumour is found in 15%–30% of cases, with a worse prognosis especially in the presence of intense nuclear expression of EGFR." (PMID 36158981, 2022). "Excitingly, the combination of EGFR-TKI with targeting ACh/M3R signaling is shown to retard tumor relapse and achieve a long-lasting drug response in vivo." (PMID 36048538, 2022). "EGFR-TKIs inhibit tumor growth by blocking the activation of EGFR in cancer cells and the downstream MAPK (RAS/RAF/MEK/ERK) and PI3K/AKT/mTOR signaling pathways." (PMID 36034789, 2022).